EGFR (epidermal growth factor receptor)
Diseases named in the same sentence as EGFR in open-access papers (continued):
Sharing a sentence is not in itself a finding about the gene and the disease.
tumor (continued). "For epithelial CMS2/3 tumours there was a benefit from the addition of anti-EGFR when added to both oxaliplatin and irinotecan-based chemotherapy, which was only observed in left-sided primary tumours." (PMID 34253874, 2021). "In A431 tumor-xenografted mice, tumor-to-kidney ratios were higher for the bivalent anti-EGFR Nb fused to an ABD compared to the bivalent anti-EGFR Nb." (PMID 34575943, 2021). "EGFR amplification was observed in 7/26 (27%) OSCCs from patients <50 years with an average of >20 copies per tumor." (PMID 34912708, 2021). "On the other hand, other tumor-suppressing glycoproteins and -proteoglycans can inhibit EGFR activation, suppressing cell invasion and migration." (PMID 34976811, 2021). "The safety and distribution of EGFR-minicells drug delivery was tested in a human tumor xenograft mouse model." (PMID 34522211, 2021). "When EGFR is wild-type in tumor tissue, liquid biopsy can help to identify around 10% of EGFR-positive patients (one out of nine in this case series)." (PMID 34680416, 2021). "Collectively, this study identified a critical role of Notch signaling in maintaining MEC stem-like cells and tumor growth, and revealed a novel approach of co-targeting Notch and EGFR signaling as a potential effective anti-MEC treatment." (PMID 33473104, 2021). "They showed that the GPI-linked nanobodies were successfully displayed on EV surfaces and greatly improved EV binding to tumor cells in a manner dependent on EGFR density." (PMID 34283059, 2021). "Neuropilin 1 (NRP1) as a coreceptor of growth factors is involved in tumor progression that affects tumor cell viability through EGFR and ErbB2 signaling pathways." (PMID 33827418, 2021). "Our data clearly indicate that a sustained use of EGFR TKIs plus prednisone is required to suppress tumor growth." (PMID 34853306, 2021). "Thus, as an alternative approach, one may suggest that an EGFR-mediated TGFβ activation could be the underlying mechanism leading to local immune suppression and the observed “lymphocyte depletion” phenotype within EGFR overexpressing tumours." (PMID 35052732, 2021). "Here, we present a small-molecule compound D6 which selectively inhibits tumor cell growth and migration in NSCLC cells with EGFR-TKI-resistant T790M-EGFR-activated mutations (T790M-EGFR-AM), e.g., L858R/T790M, 19Del/T790M and L858R/T790M/C797S." (PMID 34903832, 2021). "We further evaluated the in vivo anti-tumor effects of D6 on erlotinib-resistant NCI-H1975 cells expressing L858R/T790M EGFR." (PMID 34903832, 2021). "Research has shown that the site of the primary tumour influences the effectiveness of anti-epidermal growth factor receptor (EGFR) agents; we avoid the use of an anti-EGFR agent in right-sided primary tumours, even if RAS/BRAF wild type." (PMID 34440099, 2021). "They further demonstrated that the proportion of Tregs was decreased by coculturing these cells with conditioned medium from EGFR-mutated NSCLC cells with CD73 knockdown, and that an anti-CD73 antibody suppressed tumor growth in immunocompetent mice." (PMID 34885068, 2021). "EGFR is expressed in multiple organs and plays important roles in proliferation, survival, and differentiation of cells in both physiology and tumor development." (PMID 34877077, 2021). "Detecting EGFR exon 20 p.T790 M (p.T790 M) is much more challenging due to its limited availability in tumor tissues." (PMID 33932095, 2021). "The enhanced expression of integrin αvβ3 is observed in tumor tissues of patients resistant to EGFR inhibitors." (PMID 34976811, 2021). "EGFR is an important member of the family of the membrane-bound tyrosine kinase receptors activated in tumor cells of epithelial origin." (PMID 34711249, 2021). "A similar trend in tumor uptake observed in DLD-1 xenograft was seen in EGFR positive MDA-MB-231 which has medium EGFR expression." (PMID 33535661, 2021).
tumor (continued). "EGFR is highly expressed in tumor cells in patients with GBC and plays critical roles in the growth and progression of many solid tumors." (PMID 32989241, 2021). "The levels of E-cadherin and EGFR protein were decreased in the tumor samples from DCN-overexpressing MDA-IBC3 and SUM149 xenografts, as shown by western blotting and immunohistochemical staining." (PMID 33452400, 2021). "Both epithelial- and mesenchymal-associated genes were commonly expressed at higher levels in CTCs compared to the bulk primary tumour, although some common EMT-associated genes (CDH1, VIM, EGFR, EPCAM) remained unchanged." (PMID 34206049, 2021). "We show here that the tumour suppressor CYLD is essential for CME of EGFR and its lysosomal degradation is induced by EGF and CTX in HNSCC cells." (PMID 35008337, 2021). "Evaluation of antibodies against other epithelial or tumor-based markers, such as Mucin 1 and epidermal growth factor receptor, for detection of epithelial-derived CTCs in cats would be worthwhile." (PMID 33614766, 2021). "EVs expressing membrane glycosylphosphatidylinositol (GPI) fused with anti-EGFR nanobodies target tumor cells with even more specificity." (PMID 34830787, 2021). "According to one line of research, tumours that overexpress the EGFR grow autonomously and become “addicted” to growth factor signalling." (PMID 35052732, 2021). "This study showed a significantly reduced progression-free survival in patients with high (nuclear) ERα (and EGFR) tumor levels." (PMID 34830915, 2021). "Previous studies, in fact, showed that EGFR gene overexpression was significantly related to tumor stages, metastasis, and well-differentiated tumors." (PMID 33672900, 2021). "EGFR signaling is required to sustain the uncontrolled proliferation in tumor initiation and progression of GBM." (PMID 33959491, 2021). "Initial investigations revealed that EGFR-mutated NSCLC has lower PD-L1 expression and a low tumor mutational burden, thus leading to weak immunogenicity." (PMID 34113560, 2021). "Although the sample size is small in this exploratory trial, the success of this approach will help expand the testing scale, extending to other EGFR-TKIs and a variety of other tumours." (PMID 34332557, 2021). "Subsequently, based on the IdyllaTM method, the timeframe from tumor sampling to the initiation of EGFR-TKI was 7.7 ± 1.2 wd (11.4 ± 3.1 cd), while it was 20.3 ± 6.7 wd (27.2 ± 8.3 cd) with the NGS method (p < 0.001)." (PMID 34898548, 2021). "In multiple tumor types, activation of EGFR signaling is often accompanied by the reproduction of angiogenic factors, including VEGF." (PMID 34680445, 2021). "Across 32 different tumor types, the frequency of EGFR amplification was the highest in patients with GBM." (PMID 33959491, 2021). "BJ extract was demonstrated effective against tumor development of NSCLC cells with EGFR carrying T790M/L858R." (PMID 35582384, 2021). "It has been recognized that epidermal growth factor receptor (EGFR) was overexpressed during the progression of a number of tumor types, and thus, suppressing the EGFR signaling pathways was an effective therapeutic target in treating cancers." (PMID 34885972, 2021). "Recent studies are, therefore, trying to combine chemotherapies and immunotherapy in order to increase sensitivity to immunotherapy by modulating the tumor microenvironment for patients with EGFR-mutant NSCLC." (PMID 34638411, 2021). "The GBC tumor growth rate was 60% lower in xenograft-bearing mice treated with Anti-EGFR-CIL-miR-135a as compared to controls." (PMID 34072348, 2021). "In brief, we found that inhibition of SHP2 in EGFR T790M mutant LUAD cells can improve the sensitivity of tumor cells to Osimertinib, and the mechanism is that inhibition of SHP2 suppresses the CSCs by blockade of CXCL8-CXCR1/2 positive feedback loop." (PMID 34217295, 2021).
tumor (continued). "PLA results from tumor tissue samples indicate that HER2 heterodimerization with EGFR and HER3 proteins is decreased in both the treatment group of SA-5 alone and SA-5-Dox-LP as compared to the control group." (PMID 33800723, 2021). "On the contrary, the overexpression of LRIG1 alleviates the expression level of EGFR (either mutant or wild-type) and suppresses tumor expansion." (PMID 34576152, 2021). "The dysregulation of c-MET and HGF in tumor progression and invasion interplay with other signaling pathways, such as the EGFR pathway." (PMID 34722241, 2021). "These CART.BiTEs were shown to be effective when administered intracranially to mice bearing brain tumors, with the CART.BiTEs directly killing EGFRvIII+ tumor cells, while also redirecting endogenous T cells to kill WT EGFR+ tumor cells." (PMID 34868044, 2021). "Subsequently, all variants were tested for their capacities to elicit tumor cell killing using EGFR-overexpressing tumor cell line A431 and PBMCs-isolated NK cells as an effector cell population." (PMID 34759924, 2021). "Combining ABBV-321 and Depatux-M resulted in greater tumor growth inhibition in an EGFR-overexpressing GBM PDX model compared to either monotherapy treatment." (PMID 34926242, 2021). "Lapatinib, the small molecule tyrosine kinase inhibitor which targets HER2 and EGFR, has considerable anti-tumor activity against HER2+ BC cells, including trastuzumab resistant cells." (PMID 33842315, 2021). "EGFR immunohistochemical staining of 59 tumor specimens from 35 HGG patients was scored by pathologists and expression levels were compared to that of mouse xenografts." (PMID 33707521, 2021). "The angiogenesis of tumor serves as another mechanism related to the resistance to EGFR-TKIs which nourishes the tumor cells and enables the cells to invade to the stroma and further metastasis." (PMID 34715776, 2021). "When anti-EGFR was added to CAPOX/FOLFOX in CMS4 tumours even a detrimental effect was seen (HR 2.76, 95% CI 1.27–6.01, P = 0.006)." (PMID 34253874, 2021). "Predictive biomarkers include activating mutations in EGFR, BRAF, KRASG12C, and ERBB2, rearrangements in ALK, ROS1, RET, and NTRK, MET amplification or exon 14 skipping mutations, PD-L1 expression, and tumor mutational burden." (PMID 34425853, 2021). "Results showed an enhanced EGFR siRNA uptake efficiency in EGFR gene silencing–tumor cells as well as tumor growth inhibition." (PMID 34575510, 2021). "As an example, a patient with EGFR amplified SCC of the oesophagus had prolonged tumour control with cetuximab and irinotecan in the present study." (PMID 34794033, 2021). "Here, using the OSCC model, we demonstrate a negative regulatory role for CPAP, an essential centriole biogenesis protein, in tumor prevention by keeping the EGFR signaling regulated and EMT at bay." (PMID 33889303, 2021). "EGFR expression was significantly higher (P < 0.0001) in viable tumor core (88%, n = 30) and infiltrative tumor margin (91%, n = 39) compared to normal brain (32%, n = 23)." (PMID 34158840, 2021). "A patient-specific response was observed which correlated with EGFR levels exhibited in the tumor and corresponding organoids." (PMID 33816288, 2021). "It was specifically lethal against tumor cell lines with high levels of EGFR expression and suitable for treating EGFR-positive solid tumors." (PMID 34193050, 2021). "Hyperactive EGFR signaling promotes tumor cell growth, survival, angiogenesis, and metastasis through upregulating activation of downstream kinase cascades." (PMID 34765548, 2021). "This gene plays a key role in the protection of the tumor from hypoxia and leads to enhanced ability of tumors by stimulation with Wnt and EGFR." (PMID 34202278, 2021). "This is consistent with previous reports that DHA specifically targets tumor subtypes, attenuating EGFR nanoclustering." (PMID 33515553, 2021).
tumor (continued). "Bispecific γδ T cell engager is being developed, the antibody targeting Vγ9Vδ2 on γδ T cells and EGFR on tumors cells was demonstrated to induce strong activation of Vγ9Vδ2 T cells and cytotoxic lysis of tumor cells in a mouse xenograft model." (PMID 34039409, 2021). "EGFR activation is possibly responsible for the uninflamed TME in this type of tumour and participates in immunosuppression and immune escape." (PMID 34631565, 2021). "The Ras/MAPK and PI3K/PKB signaling pathways are two of the most studied EGFR pathways, both of which have a well-established role in tumor development, survival, and progression." (PMID 34447695, 2021). "We next assessed CDCA3 transcript levels by bioinformatics analysis of TCGA datasets of LUAD NSCLC comparing EGFR wild-type and mutant tumours." (PMID 34572879, 2021). "In bladder cancer, overexpression of EGFR on the luminal surface is frequently seen and it correlates with higher tumor staging and a poorer prognosis." (PMID 34805097, 2021). "VEGF and EGFR are multifunctional cell regulatory factors that promote the formation and growth of tumor vessels, which play an important role in tumor growth, invasion, and metastasis." (PMID 35069035, 2021). "The development of first-generation low-weight EGFR inhibitors (EGFRi), gefitinib and erlotinib, relied on frequent overexpression of this receptor in diverse tumor types, especially in non-small cell lung cancer (NSCLC)." (PMID 34681592, 2021). "Inhibition of this signal using EGFR inhibitors can, therefore, induce cell death in tumour cells and lead to tumour shrinkage." (PMID 35052732, 2021). "The first-generation of EGFR TKIs (erlotinib and gefitinib) reduce autophosphorylation and receptor activation, resulting in tumor regression through apoptosis induction and inhibition of proliferation and angiogenesis." (PMID 33916986, 2021). "The previous study found that RAW/LR5 macrophages produced heterotypic TnTs with tumor cells and this required EGFR signaling." (PMID 33450985, 2021). "Recently, an anti-EGFR nanobody fused with the 5B9 tag at its C-terminal was shown to activate and redirect the UniCAR-T cell to the EGFR-positive tumor cells both in vitro and in a mouse tumor xenograft model." (PMID 33567640, 2021). "Grade 2–3 ST (HR, 0.51; CI 95%, 0.29–0.89; p = 0.019) and RAS/BRAF/EGFR WT circulating tumor DNA (ctDNA) (HR, 0.50; CI 95%, 0.27–0.9; p = 0.019) had a statistically significant effect on OS at univariate analysis." (PMID 34830870, 2021). "The results showed that the EGFR/PI3K/Akt signaling pathway was inhibited in the tumor, which considerably weakened the tumor angiogenesis ability." (PMID 33768139, 2021). "Although half the patients (n = 2) did not have pretreatment samples, the remaining 2 patients (P16 and P17) likely acquired FGFR fusions as alternative mechanisms to combat the anti-tumor activity of EGFR TKIs." (PMID 33710807, 2021). "The expression by the CAR-T cells avoid systemic exposure to the EGFR BiTE which would have resulted in “on-target, off-tumor” toxicity." (PMID 33874996, 2021). "Due to the main modulation of tumor cell growth, signaling, and survival, EGFR is a good candidate for tumor-targeted anticancer therapy." (PMID 33918836, 2021). "For example EGFR FISH-positive tumours almost invariably overexpress EGFR RNA (and EGFR protein), but up to 50% of EGFR FISH-negative tumours also have high EGFR RNA and protein." (PMID 33169187, 2021). "Immune checkpoint inhibitors are more efficacious than chemotherapy in NSCLC patients with EGFR wild-type, KRAS mutation, and any PD-L1 tumor proportion scores." (PMID 33725808, 2021). "Our study identified novel mechanisms for EGFR-mediated tumor immune escape, and provided promising immunotherapeutic strategies for patients with EGFR-activated NSCLC." (PMID 33537094, 2021).
tumor (continued). "As a consequence, the TAT from tumor sampling to initiation of EGFR-TKIs was reduced by two weeks when the decision was based on the IdyllaTM method compared to when the decision was based on the NGS method." (PMID 34898548, 2021). "It has been found that exosomes isolated from different tumor cells that express amphiregulin (AREG) can induce the activation of EGFR in recipient cells, which subsequently affects the microenvironment or promotes bone metastases." (PMID 33855679, 2021). "In vitro biological studies of both the complexes indicated their ability to inhibit EGFR phosphorylation, a key step for controlling tumor growth." (PMID 33670650, 2021). "In spite of the effective treatment, it is still difficult to completely cure patients due to the developed resistance of tumor to the EGFR inhibitors." (PMID 34512175, 2021). "Overall, this suggests that gastroesophageal cancer patients with EGFR-driven tumours (as identified by EGFR CNG) benefit from, and are more sensitive to, PBC." (PMID 33169187, 2021). "Practically, treatment of established tumours with an EGFR inhibitor erlotinib prompted a dose-dependent increase in intratumoural T cells." (PMID 33671588, 2021). "For example, the administration of tarloxotinib in mice bearing the EGFR-mutant positive NSCLC tumour PC9 is observed to eliminate tumour hypoxia, as detected by pimonidazole (hypoxyprobe) binding three days later." (PMID 33923305, 2021). "A second IL-2 design fuses IL-2 to an antibody, such as epidermal growth factor receptor, which “actively” targets specific proteins on tumor cells." (PMID 33986267, 2021). "It has been demonstrated that both oncogenic EGFR signaling and tumor ECM resembling substrate stiffness initiate the invasive transition of benign and originally non-invasive breast gland acini." (PMID 34440749, 2021). "Olaparib, a poly (ADP-ribose) polymerase inhibitor (PARPi), was shown to suppress MDSC migration, increasing the anti-tumor activity of epidermal growth factor receptor (EGFR) vIII-targeted CAR (806-28Z CAR) T-cells." (PMID 34065010, 2021). "Cetuximab treatment slightly increased the number of apoptotic cells in tumor tissues with high EGFR expression, although a little difference was found in the number of apoptotic cells in the tumor tissues with low EGFR expression." (PMID 32989241, 2021). "A variety of EGFR-targeting molecules have been utilized to effectively and selectively deliver nanocarriers to tumor stroma, including monoclonal antibodies, single-chain antibodies, nanobodies, affimers, affinity peptides, and oligonucleotide aptamers." (PMID 34207383, 2021). "Other data are available concerning cfDNA analysis of patients with EGFR positive tumor tissue at baseline, treated by first-line osimertinib." (PMID 34638411, 2021). "As shown herein, a bi-specific CD19-bridging protein containing an anti-Her2 and an anti-EGFR scFv killed tumor cell expressing one or the other antigen, while showing exceptional potency when both antigens were present." (PMID 33735268, 2021). "In cancers such as head and neck, where the majority of tumours overexpress EGFR, antibodies inducing effects such as ADCP and ADCC are clinically relevant." (PMID 34069119, 2021). "We also identified Areg mRNA as a direct target of TTP, and showed that inhibition of the EGFR pathway strongly decreased tumor burden in Zfp36ΔEP mice." (PMID 33497366, 2021). "Further, tumor uptake of [89Zr]ZrDFO-amivantamab was significantly higher than those of the radiolabeled single-arm parent antibodies [89Zr]ZrDFO-α-EGFR or [89Zr]ZrDFO-α-c-MET." (PMID 33986665, 2021).